NQO1 (NAD(P)H quinone dehydrogenase 1)
Diseases named in the same sentence as NQO1 in open-access papers (continued):
Sharing a sentence is not in itself a finding about the gene and the disease.
breast carcinoma (continued). "NQO1 is a downstream gene of Nrf2 and is expressed in tumor tissues such as breast cancer and gastric adenocarcinoma, indicating a poor outcome in these tumor types." (PMID 28501854, 2017). "NQO1 knockdown significantly protected breast cancer cells from β-lapachone-induced cell death in MCF-7 and MDA-MB-231 cells, compared with control group." (PMID 28578385, 2017). "As a NQO1 activator, β-lap exhibited a novel anti-cancer activity in NQO1-postive breast cancer cells." (PMID 28578385, 2017). "NQO1 knockdown in human colorectal and breast cancer cell lines suppresses HIF-1 signalling and tumour growth." (PMID 27966538, 2016). "The positive rate of NQO1 protein expression was 84.7% (149/176) in breast cancers, which was significantly higher than that in hyperplasia (36.7%, 8/22) and adjacent non-tumor tissues (30.8%, 16/52) (P < 0.001)." (PMID 24499631, 2014). "Immunofluorescence staining was also performed to detect the subcellular localization of NQO1 protein in MCF-7 breast cancer cells." (PMID 24499631, 2014). "This study aimed to explore the clinicopathological significance of NQO1 and as a prognostic determinant in breast cancer." (PMID 24499631, 2014). "In this study, we demonstrated the clinicopathological significance of NQO1 through prognostic evaluation of NQO1 overexpression in breast cancers." (PMID 24499631, 2014). "The staining results clearly showed that NQO1 protein is mainly located in the cytoplasm in MCF-7 breast cancer cells." (PMID 24499631, 2014). "IHC staining also showed that NQO1 protein is mainly located in the cytoplasm of breast cancer cells." (PMID 24499631, 2014). "Further multivariate analysis using the Cox proportional hazards model revealed that NQO1 overexpression emerged as a significant independent prognostic factor for survival along with clinical stage and Her2 expression in breast cancer (P = 0.040)." (PMID 24499631, 2014). "The correlations between NQO1 overexpression and the clinical features of breast cancer were evaluated using chi-square test and Fisher’s exact tests." (PMID 24499631, 2014). "A comprehensive analysis of the molecular mechanism of NQO1 involved in the tumorigenesis and progression of breast cancer is essential." (PMID 24499631, 2014). "The strongly positive rate of NQO1 protein was 61.9% (109/176) in breast cancer, and was significantly higher than in DCIS (31.1%, 14/45), hyperplasia tissues (13.6%, 3/22) and adjacent non-tumor tissues (13.5%, 7/52)." (PMID 24499631, 2014). "Fagerholm’s in vitro experiments proved that breast cancer cells with TT genotype were resistant to epirubicin, which can be partly attributed to decreased expression of NQO1." (PMID 25545243, 2014). "Totally, 40 cases of malignant tumors, including lung cancer, breast cancer, gastric cancer and colon cancer, were selected to measure the in vivo expression of Nrf2, Mrp1, and NQO1 as well by IHC." (PMID 23667609, 2013). "In contrast, T47D human breast carcinoma cells had a low level of NQO1 activity similar to that found in human bone marrow cells, 39.7 ± 12.1 nmol.min−1.mg protein−1." (PMID 21904446, 2009). "Two likely candidate TSGs at 16q in breast cancer, NQO1 and ATBF1, were identified here as showing reduced expression in tumors with 16q LOH, but further analysis indicated that they are not target genes of LOH." (PMID 18416817, 2008). "Then, DDANQ was used to detect NQO1 activity in Hela tumor slices and human breast cancer slices." (PMID 40630553, 2025). "High‐level expression of NQO1 protein was correlated with late clinical stage in breast cancer." (PMID 39707614, 2025). "DDANQ could detect endogenous NQO1 activity in many tumor cells including Hela, A549, and MDA-MB-231 cells, and it could also be used to detect the activity of NQO1 in Hela tumor slices and human breast cancer slices." (PMID 40630553, 2025). "However, the consequences of NQO1-NF-κB interactions in breast cancer are different from those in other cancers." (PMID 36793872, 2023).
breast carcinoma (continued). "Besides, NQO1 mRNA expression was higher in males withinvasive breast carcinoma, lymphoid neoplasm diffuse large B-cell lymphoma, liver hepatocellular carcinoma, lung adenocarcinoma, and lung squamous cell carcinomathan in females." (PMID 37583897, 2023). "To evaluate the potential association of NQO1 and CKS1B expression with patient outcomes, we performed a Kaplan-Meier survival analysis using both TCGA colorectal and breast cancer datasets, which revealed a strong correlation of high NQO1 and CKS1B expression with poor prognosis." (PMID 36793872, 2023). "In this study, we showed for the first time that a new drug, IP-DNQ, exerts high cytotoxicity towards NSCLC and breast cancer cells in an NQO1-dependent manner and that it elicited efficacious antitumor responses against mice bearing A549 orthotopic lung tumors." (PMID 38136388, 2023). "Here, we report a novel combination strategy with aminooxyacetic acid (AOA), an aspartate aminotransferase inhibitor that blocks the malate-aspartate shuttle (MAS) and synergistically enhances the efficacy of β-lapachone metabolic perturbation in NQO1+ breast cancer." (PMID 35893874, 2022). "Accumulating evidence suggests that exposure to β-lap causes DNA lesions in NQO1+ NSCLC, breast cancer, and pancreatic cancer cells, resulting in PARP hyperactivation in terms of the accumulation of poly(ADP-ribose)-PARP (PAR-PARP) posttranslational protein modification." (PMID 34676172, 2021). "NQO1 is increased in many types of cancers, including breast cancer." (PMID 32922184, 2020). "It has been found that overexpression of NQO1 in breast cancer cells promotes the invasion and/or metastasis related behaviors, which may be key to developing specific inhibitors that target NQO1 signaling 41-43." (PMID 32483451, 2020). "Chrysin reduces the mRNA expression of Nrf2, MRP1, NQO-1, and HO-1 in breast cancer MCF7 cells." (PMID 33050575, 2020). "NQO1 was highly expressed in the breast cancer MCF-7 cells compared to 250MK cells." (PMID 31480790, 2019). "Reduced expression of NQO1 is associated with resistance to geldanamycin-based HSP90i such as 17-AAG and 17-DMAG, but not to structurally unrelated HSP90i in glioblastoma, oesophageal and breast cancer cells." (PMID 30678647, 2019). "Recent studies demonstrated the role of NQO1 in the cytotoxicity of a dual therapy with β-lapachone and ionizing radiation in NQO1+-MDA-MB-231 human breast cancer cells, and the induction of mitochondria-mediated cell death through ERS induced JNK pathway activation." (PMID 31388334, 2019). "In this paper, we reported that bL could decrease BSCS marker expression and inhibit the ability of breast-cancer cells to form mammospheres in an NQO1-dependent manner." (PMID 30513573, 2018). "Thus, in the present study, we detected the expression level of NQO1 in breast cancers, and validated the therapeutic effects of β-lap in breast cancers cells." (PMID 28578385, 2017). "In addition, we investigated the role of NQO1 in breast cancer cell motility inhibited by β-lap using wound-healing assay." (PMID 28578385, 2017). "IHC analyses were also performed to evaluate NQO1 expression in breast cancer patient samples." (PMID 28578385, 2017). "β-lap could represent as a promising new agent for the development of novel and effective strategies for preventing the progression of NQO1-postive breast cancer." (PMID 28578385, 2017). "The results revealed that NQO1 expression was significantly up-regulated in breast cancers." (PMID 28578385, 2017). "In subgroup analysis stratified by ethnicity, the NQO1 Pro187Ser polymorphism presented a risk factor for breast cancer in Caucasian populations, but not in Asian and Arab subjects." (PMID 24884893, 2014).
breast carcinoma (continued). "The high proportion and prognostic value of NQO1 expression suggests that NQO1 may be a significant biomarker and a potential therapeutic target for patients with breast cancer." (PMID 24499631, 2014). "NQO1 protein showed a mainly cytoplasmic staining pattern in breast cancer." (PMID 24499631, 2014). "In addition, overexpression of NQO1 showed a correlation with the clinical stage of breast cancer, which was higher in advanced stage (stage III–IV) breast cancers than in early stage (stage I–II) cases (P = 0.008)." (PMID 24499631, 2014). "High-level expression of NQO1 protein was correlated with late clinical stage, poor differentiation, lymph node metastasis, Her2 expression and disease-free and 10-year overall survival rates in breast cancer." (PMID 24499631, 2014). "Moreover, multivariate analysis suggested that NQO1 emerged as a significant independent prognostic factor along with clinical stage and Her2 expression status in patients with breast cancer." (PMID 24499631, 2014). "High NQO1 activity and expression are seen in many human tumors, including carcinoma of the liver, colon, breast, brain, and lung, and NQO1 has been shown to be an important factor in β-lapachone-induced cell death in many kinds of cancer cells, including breast cancer, glioma, and prostate cancer." (PMID 24505400, 2014). "In the present study, univariate survival analysis revealed that tumor histological grade, clinical stage, LN metastasis, Her2 expression level and NQO1 expression status are all significantly related with DFS and10-year OS rates of patients with breast cancer (P < 0.05)." (PMID 24499631, 2014). "Our study with NQO1 protein expression in breast cancers also indicated that as an exploitable cancer target, NQO1 might improve patient management and outcome by personalized therapy." (PMID 24499631, 2014). "Since NQO1 activity has been positively correlated with β-lapachone cytotoxicity in breast cancer cell lines, we examined whether the sensitivity of the different lung cancer cell lines to β-lapachone toxicity was associated with intracellular NQO1 expression." (PMID 24505400, 2014). "Univariate analysis demonstrated that histological grade (P = 0.004), clinical stage (P = 0.008), LN metastasis (P = 0.005), Her2 expression levels (P = 0.019), and NQO1 expression status were significantly associated with DFS and 10-year OS in patients with breast cancer." (PMID 24499631, 2014). "We did not observe a significant association between NQO1 Pro187Ser polymorphism and breast cancer risk when all studies were pooled into the meta-analysis." (PMID 24884893, 2014). "Similarly, the strongly positive rate of NQO1 expression was 61.9% (109/176) in breast cancers, which was also significantly higher than that in hyperplasia (13.6%, 3/22) and adjacent non-tumor tissues (13.5%, 7/52) (P < 0.001)." (PMID 24499631, 2014). "However, the clinicopathological significance of NQO1 protein expression in breast cancer is less clear." (PMID 24499631, 2014). "In this study, we performed IHC staining of NQO1 protein in breast cancer tissue." (PMID 24499631, 2014). "In breast cancer tissue, the expression of Nrf2, Mrp1 and NQO1 was significantly high (panel d2, d3 and d4), though mild expression of them could be seen in adjacent non-tumor tissue (panel c2, c3 and c4)." (PMID 23667609, 2013). "This phenomenon could be attributed to the inability of polymorphic NQO1 to stabilize TAp63, whose expression was indeed shown to be significantly reduced in breast cancers." (PMID 20613985, 2010). "We hypothesized that if NQO1 is a candidate target for LOH at 16q, there should be preferential loss of the active C-allele in breast cancer." (PMID 18416817, 2008). "A possible role for NQO1 in breast cancer would be confirmed if it could be shown that LOH at 16q is targeted at the active allele." (PMID 18416817, 2008).
breast carcinoma (continued). "Indeed, STAT1 signaling downregulates NQO1, a key ROS scavenger, in many breast cancer models." (PMID 34083537, 2021). "Finally, it is noteworthy that NQO1-positive breast cancer cells correlate with the malignancy of the disease and could be used as a prognostic biomarker for breast cancer." (PMID 32085381, 2020). "Our data also clearly demonstrated that β-lapachone treatment sensitized the radioresistant 231-RR cells or Hs578t cells toward radiation, suggesting that β-lapachone could be potentially developed as a radiosensitizer in breast cancers with an increased NQO1 activity." (PMID 32922184, 2020). "Additionally, we investigated the relationship between NQO1 expression and the clinicopathological parameters of the 221 cases of breast cancers, and significant correlations of NQO1 expression with tumour grade, clinical stage, Her2 status and lymph node metastasis." (PMID 28578385, 2017). "However, the expression level of NQO1 and the therapeutic potential of β-lap in breast cancer are unknown." (PMID 28578385, 2017). "However, the strongly positive rate of NQO1 protein was significantly higher in Grade 2 and Grade 3 breast cancers than in Grade 1 cases (P = 0.004), and it was also higher in breast cancers with lymph node metastasis than in cases without metastasis (P = 0.005)." (PMID 24499631, 2014). "NQO1 is a detoxifying reductase, where lack of function in somatic cells is related to increased benzene oncogenesis and inactivating polymorphism has been related to dismal prognosis and predictive of treatment failure in breast cancer." (PMID 22905093, 2012). "Despite its clinical activity, most promisingly in trastuzumab-refractory ErbB2-positive breast cancer, 17-AAG suffers from a limited aqueous solubility, low oral bioavailability, susceptibility to the metabolic activities of polymorphic enzymes (CYP3A4 and NQO1/DT-diaphorase), and hepatotoxicity." (PMID 22984537, 2012). "Six ferroptosis-related genes (SLC7A11, GPX4, FTH1, NQO1, NFE2L2, SQSTM1) demonstrated consistent upregulation across all breast cancer subtypes, with higher expression observed in more aggressive tumors." (PMID 42074090, 2026). "NRF2 knockdown had a pronounced effect on gene expression in MDA-MB-436 breast cancer cells, notably reducing multiple anti-ferroptosis genes, including SLC7A11, NQO1, TXNRD1, GCLM, and AKR1C1." (PMID 40867343, 2025). "Our previous work demonstrated that NQO1 can bind to pyruvate kinase L/R (PKLR), a key regulator of glycolytic reprogramming in breast cancer, thereby activating the AMPK and AKT/mTOR signaling pathways and inducing glycolytic reprogramming." (PMID 39939940, 2025). "The same results were also observed in human breast cancer slices imaging experiment, and the fluorescence intensity of DDANQ produced by NQO1 metabolism decreased significantly after the addition of inhibitor β-lapachone." (PMID 40630553, 2025). "This study provides novel preclinical evidence supporting IP-DNQ efficacy in NQO1+ NSCLC and breast cancer cells." (PMID 38136388, 2023). "Using siRNA to silence Cul3 in breast cancer cells, microarray analysis revealed that the expressions of oxidative stress downstream genes (AKR1C1, UGDH, TXN, GCL, and NQO1) were overexpressed at least 2-fold." (PMID 35242279, 2022). "We next compared steady-state NQO1, STAT1, and pY701-STAT1 protein levels across a panel of human breast cancer cell lines spanning various subtypes." (PMID 34083537, 2021). "The NQO1:CAT ratios are suggested to be a therapeutic window in NSCLC, pancreatic and breast cancers." (PMID 34676172, 2021). "Although we do observe an inverse relationship between NQO1 and STAT1 levels in these breast cancer PDXs, the NQO1/STAT1 ratio is not sufficient to predict relative sensitivity to combined β-lapachone/phenformin treatment." (PMID 34083537, 2021).
breast carcinoma (continued). "Overexpression of NAD(P)H:quinone oxidoreductase-1 (NQO1) regulates the expression of pyruvate kinase in the liver and the red blood cells (PKLR) to mediate EMT in breast cancer." (PMID 32793598, 2020). "Recently, we found that some antioxidant enzymes, including NQO1, were overexpressed in MCF-7 breast cancer cells chronically exposed to hydrogen peroxide (H2O2) and by consequence becoming resistant against such oxidative stress, the so-called Resox cells." (PMID 31480790, 2019). "We first measured NQO1 expression in three cell lines: The normal human mammary epithelial 250MK, MCF-7 breast cancer, and Resox (MCF-7 resistant to an oxidative stress) cells." (PMID 31480790, 2019). "By using miRNA arrays, Eades and coworkers found that forced reexpression of miR-200a, normally repressed in breast cancer cells, was able to impair KEAP1 mRNA translation, inducing NRF2-mediated NQO1 transactivation." (PMID 31097977, 2019). "To assess the possible clinical relevance of NQO1 and GCLC, we determined if their mRNA levels showed any prognostic value in human breast cancer patient cohorts, with long-term follow-up (nearly 20 years)." (PMID 28411284, 2017). "The data showed after NQO1 knocked down, the inhibition on the migration and EMT progress of breast cancer cells by β-lap were significantly reduced." (PMID 28578385, 2017). "In conclusion, these results demonstrated that NQO1 could be a useful prognostic biomarker for patients with breast cancer, and its bioactivatable drug, β-lapachone represented a promising new development and an effective strategy for indicating the progression of NQO1-positive breast cancers." (PMID 28578385, 2017). "However, the clinical significance of NQO1 expression status in breast cancer remains unclear." (PMID 24499631, 2014). "In agreement with previous studies, we found that staining of NQO1 is mainly localized in the cytoplasm, and these observations were consistent with our IF staining results in MCF-7 breast cancer cells." (PMID 24499631, 2014). "Breast cancer proliferative genes, such as aurora kinase, ERCC1, IGFBP3 were inhibited and growth inhibitory genes, such as NQO1, PTPRJ were activated by GTx-027." (PMID 25072326, 2014). "Furthermore, our IHC results showed that the positive rate of NQO1 protein in DCIS was also significantly higher than either hyperplasia or adjacent normal tissues, indicating that NQO1 upregulation may occur in the initiation stage of breast cancer progression." (PMID 24499631, 2014). "The nanodrugs could be internalized into breast cancer cells through both clathrin and CAV‐1‐mediated endocytosis and generate ROS in an NQO1‐dependent manner." (PMID 40150864, 2025). "Consistent with previous reports 3,40, we found that expression levels of NQO1 and CKS1B reported in TCGA colorectal and breast cancer datasets were higher in colorectal and breast cancer compared with normal tissues and that CKS1B expression was dependent on the level of NQO1 expression." (PMID 36793872, 2023). "To this end, we utilized MDA-MB-231 NQO1+, MDA-MB-231 NQO1−, MDA-MB-468, and T47D breast cancer cells to test the hypothesis that β-lap and AOA combinatorial treatment synergistically reduces metabolic turnover in an NQO1 dependent manner." (PMID 35893874, 2022). "However, oestrogen has been shown to recruit ERα to the NQO1 promoter, resulting in inhibited transcription of NQO1, an NRF2-dependent detoxification enzyme, in turn contributing to breast cancer prevention." (PMID 36376959, 2022).